IFNG (interferon gamma)
Diseases named in the same sentence as IFNG in open-access papers (continued):
Sharing a sentence is not in itself a finding about the gene and the disease.
COVID-19 (continued). "Other upregulated functions in COVID-19 patients included processes related to acute inflammatory responses, response to interferon gamma, pattern recognition receptor activity, antigen binding, and platelet activation, as well as negative regulation of viral genome replication." (PMID 33138195, 2020). "Inflammatory cytokines such as TNF-α, interferon gamma (IFN-γ), interleukin 6 (IL-6), and IL-10 present in the plasma of COVID-19 patients induce mitochondrial reactive oxygen species production and impede mitochondrial oxidative phosphorylation and ATP production among other effects." (PMID 32854430, 2020). "Strikingly, lower secretion of IFNγ correlated with increased severity of COVID-19 (p < 0.0001)." (PMID 33585507, 2020). "This is in accordance with other pro-inflammatory cytokines that were reportedly increased in the peripheral blood of patients with COVID-19, such as the Th-17 inducing cytokine IL-6, IL-10, IL-2 and the Th1 signature cytokines interferon gamma (IFN)-γ and tumor necrosis factor (TNF)-α." (PMID 32512702, 2020). "BET inhibitors can also affect innate and adaptive immune responses, through processes such as repression of IFNG (IFN gamma), which could potentially attenuate the cytokine storm associated with COVID-19." (PMID 33310900, 2020). "Thus, it is hypothesized that an optimal vitamin D level may modulate the inflammatory response by reducing the activity of interleukin-6 (IL-6) and interferon gamma (IFNγ), two predictors of unfavorable clinical outcome in severe COVID-19." (PMID 40427060, 2025). "In a mouse model of severe acute respiratory syndrome coronavirus 2 (SARS-CoV-2) infection, hemophagocytic lymphohistiocytosis, and sepsis, blocking tumor necrosis factor-alpha (TNF-α) and interferon-gamma (IFN-γ) prevents cell death and reduces the development of cytokine storm." (PMID 41142251, 2025). "The role of IL-10 and IFNγ might differ during uncontrolled viral replication or severe COVID-19." (PMID 38950078, 2024). "Common COVID-19 symptoms such as fever and ageusia were associated with IFNγ ELISpot positivity in seropositive participants, whereas no participant characteristics were associated with IFNγ ELISpot positivity in seronegative participants." (PMID 38686954, 2024). "Acute COVID-19 children had significantly elevated levels of cytokines, (Interferon (IFN)) IFNγ, Interleukins (IL)-2, TNFα, IL-1α, IL-1β, IFNα, IFNβ, IL-6, IL-12, IL-17A and Granulocyte-Colony Stimulating Factors (G-CSF) in comparison to convalescent COVID-19 and controls." (PMID 37013538, 2023). "While IFNG has some anti-viral functions, IFNG is associated with negative COVID-19 outcomes." (PMID 37361874, 2023). "We previously found a higher number of spike-specific IFNγ+, IL-2+, and polyfunctional IFNγ+/IL-2+ T-cells, with enhanced proliferative capacity, in aCD20-MS patients compared to a control group after primary vaccination series with two doses of mRNA-based COVID-19 vaccines." (PMID 37449202, 2023). "Similarly, another study confirmed that several serum pro-inflammatory mediators including IL-2R, IL-6, IL-10, and TNFα are increased in severe (n = 11) compared to moderate (n = 10) COVID-19 patients, while serum IFNγ levels were decreased negatively correlating with disease severity." (PMID 36941580, 2023). "In addition to the CD8+ T-cell defect, CD4+ T cells in COVID-19 cases also express the exhausted markers, and a high frequency of non-functional CD4+ T cells that are deficient at producing IFNγ, IL-2, and TNFα has been demonstrated in severe COVID-19 cases." (PMID 36839573, 2023). "The results showed that the MN-based minimally invasive intradermal vaccine effectively penetrated the skin of mice, eliciting significant B-cell antibody responses and inducing interferon-gamma (IFN-γ)-based T-cell responses, which may control the rapid COVID-19 outbreaks." (PMID 37242591, 2023).
COVID-19 (continued). "In particular, in severe COVID-19 patients the low (or even absent) quantity of IFNγ-releasing T cells in the peripheral blood could be caused by a defective induction of SARS-CoV-2 T cells." (PMID 36757971, 2023). "Furthermore, IFN-γ (IFNG) levels were more than three-fold higher in KD compared to severe COVID-19, a key observation that differentiates KD hypercytokinemia from the cytokine storm in severe COVID-19." (PMID 36159873, 2022). "Interferon gamma (IFN-γ) may be potential adjuvant immunotherapy for COVID-19 patients." (PMID 36298734, 2022). "Besides the direct impact of COVID-19 on the myocardium, another mechanism is possible via the systemic release of various pro-inflammatory cytokines such as interleukine-1 and 6, interferon gamma, macrophage inflammatory protein-1A, and tumor necrosis factor-alpha." (PMID 35740252, 2022). "Finally, some studies reported higher levels of autoantibodies (such as against IFNγ, phospholipids, and annexin A2) in COVID-19 patients, suggesting that autoantibodies may drive the worsening of the disease." (PMID 35666101, 2022). "We did not detect robust IFNγ or IL-6 expression, both of which are associated with fatal COVID-19, which may account for why the deer mice did not have significant disease or death." (PMID 34010360, 2021). "Whether promoting interleukin-18 or its consequences, such as IFNγ, might be helpful to prevent or treat COVID-19 could be considered, given these treatments are available, and a small case series suggested promising results of using IFNγ in critically ill COVID-19 patients." (PMID 34911594, 2021). "Overall, patients with severe COVID-19 infection may present with typical features of macrophage activation syndrome which is partly resulting from overwhelming IFNγ formation as reflected by higher levels of the IFNγ-inducible macrophage-derived biomarker neopterin in subjects with severe COVID-19." (PMID 34366882, 2021). "Importantly, functional experiments with K562 cells showed that NK-cell IFNγ production was significantly reduced in COVID-19 patients compared with healthy donors, which was predominantly observed in the CD56bright population associated with a significant reduction in degranulation activity." (PMID 33060840, 2021). "As the known CXCR3 ligands, CXCL9, CXCL10, and CXCL11, are predominantly induced by IFNγ, the presence of this CXCR3-expressing CD11b+CD14+ monocyte subset may be mechanistically related to the synchronous increase in the IFNγ-producing CD4+ T cell subset in our convalescent COVID-19 cohort." (PMID 34113347, 2021). "MAIT cells isolated from COVID-19 patients expressed significantly higher levels of the pro-inflammatory cytokines TNFα and IL-17A, as well as of the cytolytic protein granzyme B compared to healthy controls ex vivo, while ex vivo expression of IFNγ and perforin was unchanged." (PMID 33546489, 2021). "Finally, we investigated whether CD8 T cells from COVID-19 patients were capable of producing interferon-γ (IFNγ) after polyclonal stimulation." (PMID 32669297, 2020). "The present data indicate that DPSC administration might be effective in patients with COVID-19-induced hyper-inflammation, due to the inhibition in the production of several cytokines by activated T lymphocytes, namely, IFNγ, TNFα, IL-2, IL-9, IL-10, IL-17A, IL-18, IL-21, and IL-27." (PMID 33634100, 2020). "Extracellular ISG15 acts as a ligand for integrin ITGAL38, interacting with it and stimulating release of IFNγ and IL10 from NK cells through that interaction, with expression of IL10 being especially notable as an important factor in COVID-19 prognosis." (PMID 40374692, 2025). "This was characterized by low levels of IRF7, IFNβ1, ISG15 and IFNγ, highlighting the importance of intact TLR7 signaling in the pathogenesis of severe COVID-19." (PMID 41011507, 2025).
COVID-19 (continued). "For example, autoantibodies against interferon-gamma (IFN-γ) generated during SARS-CoV-2 infection can persist, exacerbating long COVID-19 and contributing to severe acute respiratory syndrome (SARS) by impairing host immune responses." (PMID 41149075, 2025). "Vaccination with various COVID-19 vaccines has been demonstrated to elicit spike protein-specific CD4+ and CD8+ T cell responses, which secrete interferon-gamma (IFN-γ) and tumor necrosis factor-alpha (TNF-α)." (PMID 41029649, 2025). "We then performed GSEA on DEGs per vascular cell state and observed upregulated gene sets related to IFNγ signaling in EC1, EC5 and EC6 as well as PC1 and PC3 from Post-COVID-19 patients." (PMID 39994453, 2025). "The post-vaccination cellular response to COVID-19 vaccination in AIIRD patients is profoundly impaired on many different levels, going beyond the standardly assessed production of interferon-gamma." (PMID 40226625, 2025). "IFNγ, CXCL10, and IL-6 are among many elevated proteins at baseline in all COVID-19 positive subjects relative to healthy subjects." (PMID 40424310, 2025). "IFNG, expressed primarily in CD56dim NK cells, was downregulated in severe RSV and steroid-treated severe COVID-19 (padj = 0.019)." (PMID 39877087, 2025). "Pro-inflammatory cytokines such as interleukins IL-2, IL-6, tumor necrosis factor-alpha (TNF-α), interferon-gamma (IFN-γ), and many other molecules, including chemokines, play a significant role in the pathophysiology of COVID-19." (PMID 38707035, 2024). "GSE164805 and GSE171110 dataset validation revealed significant differences between the COVID-19 and normal controls in four core genes (feature genes), namely IL6R, TLR4, TLR2, and IFNG." (PMID 38165854, 2024). "Further assessment and analysis of the SARS-CoV-2-specific T-cell memory at 4 M revealed the enhanced IFNγ+CD4+ and CD8+ memory T cell responses with increasing in the initial COVID-19 severity from mild to moderate to severe." (PMID 38811527, 2024). "In another study by our group, QuantiFERON SARS-CoV-2 assay, a fast and effective IFNγ release assay used to detect IFN-γ production from CD8+ T cells, proved effective in children with COVID-19." (PMID 39594853, 2024). "This study aimed to evaluate the association of the levels of cytokines interleukin (IL)-2, IL-6, tumor necrosis factor-alpha (TNF-α), interferon-gamma (IFN-γ), and IL-10 with the severity of COVID-19 in Bangladesh." (PMID 38707035, 2024). "Meanwhile, five proteins exert protective effects against hospitalization and progression to critical COVID-19 (OR: 0.85~0.95), including CXCL11, CDCP1, CCL4/MIP, IFNG, and LIFR." (PMID 38455043, 2024). "The CSF2, IFNG, and IL1B expression levels were considerably lower in the COVID-19 than in the Healthy group, while those of IL6R, TLR2, TLR4, and TNF were higher." (PMID 38165854, 2024). "Compared with the control group, the expression of IFNG in TCs and that of IFNGR (IFN-γ receptor) in MACs were upregulated in the COVID-19 group." (PMID 38441496, 2024). "Ex vivo stimulation of whole blood with SARS-CoV-2 antigen, resulted in lower IFNγ response in acute MIS-C compared to convalescent MIS-C and healthy COVID-19 vaccinated adults, highlighting the importance of antigen-specific immune cell exhaustion in MIS-C." (PMID 39300098, 2024). "We found 19 ncRNAs differentially expressed by at least one of IFNB, IFNG, or TNFA that are also differentially expressed in both severe COVID-19 and poor cognition." (PMID 38410515, 2024). "TNFα and IFNγ induce PANoptosis in mice that leads to CSS and death, which has been suggested to mimic severe COVID-19 in patients." (PMID 37459541, 2023). "Activated T cells and NK cells showed the strong interactions of IFNG/IFNGR with ncMono, which were enhanced as the severity of COVID-19 increased." (PMID 37095364, 2023).
COVID-19 (continued). "For instance, lung tissue specimens obtained from COVID-19 patients were enriched for cells co-expressing CCR6 and IL17A and also had high levels of IL-6, IL-17A, GM-CSF, and IFNγ found in BALF." (PMID 38179278, 2023). "Eleven genes were upregulated in all groups, including TNF, and other effector molecules, including IFNG, GZMB, and PRF1, were upregulated after vaccination in spike-specific CD4+ T cells obtained from donors with a history of mild or severe COVID-19." (PMID 38064569, 2023). "This prompted a pathway to be constructed between COVID-19 and SNCA with IFNG, ACE2, and intermediary molecules consisting of cytokines, receptors, and enzymes." (PMID 37686360, 2023). "Patients with COVID-19 typically have higher levels of leptin, TNF-∝, interleukin-1, interleukin-2 and interferon-gamma but lower levels of helper T cells, cytotoxic T cells, regulatory T cells and natural killer (NK) cells (IFN-∝)." (PMID 37297724, 2023). "Our results indicate that patients recently recovered from mild and/or severe COVID-19 show semen inflammation as evidenced by elevated seminal plasma levels of IL-1β, TNF and IFNγ with respect to control individuals." (PMID 37497433, 2023). "(C) Relative expression of IFNγ, IL-17A, TGFβ, and IL-10 genes in peripheral blood CD3+ CD4+ cells from COVID-19 patients (moderate or severe) and healthy control (HC)." (PMID 37523305, 2023). "These include interleukin-1 (IL-1), IL-6, IL-18, IL-10, interferon gamma (IFN-γ) and tumor necrosis factor-alpha (TNF-α) secreted by T helper type 1 (TH1) and other cells during the inflammatory process of COVID-19." (PMID 37447302, 2023). "The spike-specific IFNγ-releasing cells were significantly lower in SARS-CoV-2 severe patients requiring hospitalization (8 s.f.c.×106), as compared to COVID-19 mild-moderate patients (135 s.f.c.×106; p<0.001) and healthy subjects (103 s.f.c.×106; p<0.001)." (PMID 36757971, 2023). "In fact, we detected semen inflammation in patients recently recovered from mild and/or severe COVID-19 as shown by increased levels of IL-1β, TNF and IFNγ in seminal plasma." (PMID 37497433, 2023). "The activation of T cells and their ability to produce large amounts of effector cytokines (IL-2, IFNγ, and TNF) was also reflected by EVs obtained from COVID-19 patients with severe disease in the current study." (PMID 36982991, 2023). "The serum levels of interferon-gamma (IFN-γ), tumor growth factor-beta (TGF-β), and IL-8 are significantly higher in patients with COVID-19." (PMID 37896963, 2023). "In COVID-19 patients, PD-1+ CD8+ T cells have been found to express perforin and granzyme, proliferate upon re-stimulation, and express interferon gamma." (PMID 36817450, 2023). "Secondary endpoints included geometric mean fold rise (GMFR) in antibody titres; incidence of solicited local and systemic adverse events; IFNγ+ CD4+ and IFNγ+ CD8+ T-cell responses at days 7 and 28; and incidence of COVID-19." (PMID 37549680, 2023). "Early into the pandemic, those diagnosed with COVID-19 were found to display significantly elevated proinflammatory responses, including increased levels of IL-6, TNF, IL-2, IL-1β, IP-10, IFNγ, MCP1 and MIP1α." (PMID 37091818, 2023). "To confirm the role of interferon-gamma in asymptomatic patients, we analyzed data from a separate study also involving CD56dim CD16+ NK cells in COVID-19 patients of varying severity." (PMID 37147723, 2023). "Previously, our group has shown an increased level of cytokines in the antigen-specific culture supernatants including IFNγ, IL-2, IL-4, IL-13, and IL-17 in MIS-C in comparison with acute COVID-19 and other infectious diseases." (PMID 38116577, 2023). "Peptides that included residue of the N protein at 63 provided strong IFNγ release, as was demonstrated with cell sorting and ELISPOT assays in COVID-19 convalescents and peptide-vaccinated people." (PMID 36680269, 2023).
COVID-19 (continued). "The aim of this study was to evaluate a COVID-19 vaccine allergy using in vitro T-cell exposure to the tested drug with the flow cytometry measurement of CD69, CD40L, TNFa, IFNG, IL-2, IL-4, IL-6, IL-10, intracellular granulysin, and IFNgamma." (PMID 37686102, 2023). "Interleukin (IL)-1, IL-6, IL-10, tumor necrosis factor-alpha (TNF-a), interferon-gamma (IFN-γ), chemokine (C-C motif) ligand 2 (CCL-2), CXCL-9, and IL-8 are some of the additional cytokines found to be important in the pathophysiology of COVID-19." (PMID 35632654, 2022). "Previously, it was shown that CD8+ Tc1 cells able to produce IFNγ, similar to Tc2 (CD8+IL-4+) and Tc17 (CD8+IL-17A+) cells, were lowered in convalescent COVID-19 patients compared to control subjects." (PMID 36146713, 2022). "STRING database was used to analysis core intersection targets of LHQW and COVID-19, 13 core protein targets (including: NLRP3, TNF, CSF2, IFNG) were obtained by setting confidence degree (confidence degree>0.95)." (PMID 36506032, 2022). "Given the increased levels of TNF and IFNG in the plasma of patients with COVID-19, we inferred that TNF- and IFNG signaling pathways were likely to be activated in SARS-CoV-2-infected hBMECs." (PMID 35705998, 2022). "mRNA levels of ADAM17, IFITM3, IL6, CXCL10, CXCL11, IFNG and TYK2 were increased in PBCs of COVID-19 patients (n = 73) compared with controls (n = 47), independently of sex." (PMID 36009555, 2022). "According to the immunological mechanisms, both viral vector and mRNA COVID-19 vaccines induced a strong activation of CD8+ and CD4+ T cells, as well as the production of IFNγ and IL-2." (PMID 36177033, 2022). "The levels of proinflammatory cytokines/chemokines such as interleukin 6 (IL-6), IL-8, interferon gamma (IFN-γ)-induced protein 10 (IP-10), and tumor necrosis factor alpha (TNF-α) are markedly elevated in the sera of severe COVID-19 patients (4, –, 9)." (PMID 35856559, 2022). "The uncontrolled release of IL-6, IFNγ, and TNF-α can result in a downstream cascade of cytokine and cellular responses that further contribute to disease severity in both COVID-19 and malaria." (PMID 36415655, 2022). "Serum levels of IFNγ, CRP, IL-10, IL-13, IL-6, IP10, MCP-1 and IL-23 were significantly higher in COVID-19 patients than in controls after adjustment for age and BMI." (PMID 36554094, 2022). "While the main cytokine producers CD16negCD56high NK cells were found in higher proportion in asymptomatic patients with the high expression of IFNG, the CD16+CD56dim was significantly higher in patients with severe COVID-19." (PMID 36233174, 2022). "In a clinical study of 109 outpatients with COVID-19, the magnitude and quality of SARS-CoV-2-specific CD4+ T-cell response showed a shift, from IFNγ-producing cells to TNF-α-producing cells over time." (PMID 36032096, 2022). "These tests were used to detect interferon gamma (IFN-γ) and interleukin 2 (IL-2) secreting reactive T-cells in response to COVID-19 vaccination." (PMID 35510135, 2022). "In the patients with moderate COVID-19, CD8+ TTE cells showed higher expression of IFNG, TNF, CCL5, PRF1, GZMB, and GZMA, together with genes encoding cytotoxic receptors (KLRB1, KLRC1, and KLRD1) in comparison with severe cases." (PMID 36119105, 2022). "Molecular docking suggested that active ingredients (including: licopyranocoumarin, Glycyrol and 3-3-Oxopropanoic acid) in LHQW played a role in treating COVID-19 by acting on CSF2, CXCL8, CCR5, NLRP3, IFNG and TNF." (PMID 36506032, 2022). "Proteomic analysis highlighted a cytokine storm in the serum of patients with COVID-19, with elevated expression levels of IL-6, CXCL10, CXCL11, IFNγ, MCP-2, and MCP-3 detected in infected patients relative to healthy controls." (PMID 35303909, 2022). "In COVID-19, while impaired type I IFN (i.e., IFNα and IFNβ) activity has been observed in patients with a severe disease course, in vitro IFNγ production has been less studied." (PMID 36016305, 2022).